TMPRSS2 (transmembrane serine protease 2)
Diseases named in the same sentence as TMPRSS2 in open-access papers (continued):
Sharing a sentence is not in itself a finding about the gene and the disease.
infection (continued). "Interestingly, the transfection of AXL or Tim1 does not promote ACE2-mediated viral entry in cells co-transfected with TMPRSS2, and infection was insensitive to cysteine protease inhibitor E-64, indicating that PS receptors are not required for plasma membrane-mediated infection." (PMID 36423144, 2022). "However, ACE2 and TMPRSS2 are critical factors in the infection process of SARS-CoV-2." (PMID 35163355, 2022). "Interestingly, we see a stronger reduction of nuclear mRNA export following SARS-CoV-2(alpha) infection in A549-ACE2/TMPRSS2 cells compared to Vero cells, which may be due to increased ISG induction in these cells." (PMID 36007063, 2022). "Furthermore, it may result in overexpression of ACE2 and TMPRSS2, which explains the higher infection rate and disease severity in individuals with comorbidities." (PMID 36589459, 2022). "However, our study demonstrated that TLR ligands including LPS could induce cell surface ACE2 in monocytes and ACE2 and TMPRSS2 blockage partially inhibits monocyte infection by SARS-CoV-2." (PMID 36085197, 2022). "Therefore, infection is not only limited to TMPRSS2 expressing cells." (PMID 36341352, 2022). "Thus, it will be interesting to further determine whether an altered intrinsic fusogenic activity and TMPRSS2 dependency of SARS-CoV-2 VOCs affect their dependency on specific IFITM proteins for efficient infection." (PMID 35543509, 2022). "Importantly, the high expression of ACE2 in the Intestine Chip, along with expression of multiple surface proteases, such as TMPRSS2, that also help to support virus entry, enabled efficient infection of the intestinal epithelium when NL63 virus was introduced into the apical lumen." (PMID 34759819, 2021). "Because accumulated evidence has shown that the expression of TMPRSS2 enhances both SARS-CoV and SARS-CoV-2 infection, we next tested whether the coexpression of ACE2 and TMPRSS2 could mediate efficient infection of 293T cells with SARS2-S-pseudotyped lentiviruses." (PMID 33558493, 2021). "However, TMPRSS2 plays a dual role during the infection process." (PMID 34201505, 2021). "Moreover, Calu 3 cells inoculated with SARS-CoV-2 at low multiplicity of infection (MOI) showed only small foci of infection if they were previously exposed to antisense peptide-conjugated phosphorodiamidate morpholino oligomer (PPMO) leading to knockdown of TMPRSS2 activity." (PMID 33641565, 2021). "Since the cleavage at the S2′ site by TMPRSS2 necessitates the priming cleavage at S1/S2, the accumulation of FCS mutations in the progeny during the infection in HAE-ALIB15-20 and HAE-ALIKC19 may limit infection of the mut-del1 or mut-del2." (PMID 33975939, 2021). "Similarly, the TMPRSS2 inhibitor also inhibited infection of cells overexpressing TMPRSS2." (PMID 33824288, 2021). "However, the absolute gene expression levels of ACE2 and TMPRSS2 were higher in nasal brushings than in lower airway compartments, supporting a recent report that the nasal epithelium is a major site of infection." (PMID 33413387, 2021). "For the analysis of other districts, cells from the hippocampus have low expression levels of TMPRSS2 and ACE2, and the cerebellum, spinal cord, and neuronal epithelium data show zero expression of TMPRSS2 and ACE2, which demonstrates a low infection risk of these districts." (PMID 33401657, 2021). "The infection by SARS-CoV-2 initiates with the viral entry mediated through the interaction of the spike (S) protein with the host ACE2 receptor followed by cleavage of the S protein by the host transmembrane serine protease 2 (TMPRSS2) prior to the fusion to the host cell surface." (PMID 33718434, 2021). "The significantly increased infiltration of CD4 T cells and B cells in LUAD patients with high expression levels of ACE2 and TMPRSS2 may cause an imbalance in immune regulation, making patients more susceptible to SARS-CoV-2 invasion, and the inflammatory response after infection is aggravated." (PMID 33195212, 2020).
infection (continued). "Together, tissue expression of ACE2 and TMPRSS2 may determine infection." (PMID 33125431, 2020). "Taking the ocular surface for example, if TMPRSS2 was independently expressed on one cell population and the receptors on another cell type, infection could still be theoretically possible as the TMPRSS2 primed virus in the tear film could be carried to the receptor laden cell population." (PMID 32883010, 2020). "In addition, it has also been shown that SARS‐CoV‐2 uses the transmembrane protease serine 2 (TMPRSS2) for S protein priming (cleavage of the fusion domain) and the inhibition of TMPRSS2 by a clinically approved inhibitor might block further infection." (PMID 32395702, 2020). "Therefore, it can be inferred that TMPRSS2 has a greater role in infection." (PMID 32825469, 2020). "Using immunohistochemical analysis and, very recently, using single nuclei and single‐cell RNA sequencing, of lung samples from otherwise healthy subjects, ACE2 and TMPRSS2 were shown to be co‐expressed in human bronchial epithelial cells, which could be a nexus for primary infection." (PMID 32358833, 2020). "At the same time, in Vero cells engineered to overexpress TMPRSS2, with the same dosages of the drugs, E-64d could only block ~25% of the infections, whereas camostat mesylate blocked nearly ~65% of the infections, indicative again of the relative utilization of the pathways in these cell lines." (PMID 33290397, 2020). "Therefore, we postulate that if TMPRSS2 levels influence susceptibility to SARS-CoV-2, then infection risk may vary significantly across world populations as a result of the prevalence of these eQTL variants." (PMID 33046696, 2020). "Therefore, we set out to determine whether, and to what extent, MERS-CoV utilizes CD9 and TMPRSS2 during in vivo infection." (PMID 28759649, 2017). "Moreover, augmented TMPRSS2 expression was found to be associated with increased risk of severe influenza upon infection with the 2009 H1N1 pandemic virus and with increased susceptibility to H7N9 FLUAV infection." (PMID 26379044, 2015). "In the NA-pretreated group, TMPRSS2 and TMPRSS11D exhibited similar infection-enhancing effects on all three strains, leading to increased infection rates and enhanced syncytia formation." (PMID 41505483, 2026). "We transduced the cells with lentiCRISPRv2 constructs targeting either ACE2, TMPRSS2, KCNA6, or LGMN and subjected the knock-out cell lines to infection with replication competent SARS-CoV-2." (PMID 40674406, 2025). "RNA-seq reveals co-expression of ACE2 and TMPRSS2 in healthy lung tissue AT2 cells, considered the primary site of infection." (PMID 40631549, 2025). "The results from infection of Vero E6 cells and Vero cells expressing human ACE-2 and TMPRSS2 indicate the greatest replication capacity for BA.1, followed by Gamma." (PMID 40718679, 2025). "The findings indicate that infection occurs primarily in areas where both ACE2 and TMPRSS2 are present." (PMID 39858469, 2025). "Only basal activity levels of TMPRSS2 in host cells can support the SARS‐CoV‐2, influenza A and influenza B entry and infection." (PMID 40375579, 2025). "Infection of human A549 lung epithelial cells expressing ACE2 and TMPRSS2 with SARS-CoV-2 revealed c-Jun phosphorylation in cells positive for dsRNA, implying JNK activation specifically within SARS-CoV-2-infected cells." (PMID 40968155, 2025). "To test the possibility of using human DPP4 for infection, we used the human HOS cell line stably expressing human DPP4 and TMPRSS2 (HOS-hDPP4/TMPRSS2) as target cells for pseudovirus infection." (PMID 40740328, 2025). "For both pretreatment periods, the infection rate was reduced at different time points, enforcing the functional relevance of the ACE2 and TMPRSS2 downregulation." (PMID 40141308, 2025). "(F) SARS-CoV2-PP infection assay in HEK293T cells expressing ACE2, TMPRSS2, and each of designated membrane protein." (PMID 41147561, 2025).
infection (continued). "Treatment with the anti‐androgen drug enzalutamide reduced TMPRSS2 levels in human and mouse lungs and significantly reduced SARS‐CoV‐2 entry into lung cells and infection." (PMID 38923119, 2024). "Successful infection of a host cell depends on the presence of various surface host proteins, including but not limited to ACE2 and TMPRSS2." (PMID 39640372, 2024). "The spike protein-mediated and TMPRSS2-dependent SARS-CoV-2 infection model with lung organoids was verified, and drugs that can prevent infection were tested by treating the cells with the TMPRSS2 inhibitor camostat, then quantifying luciferase activity." (PMID 38909262, 2024). "In this study, we show that inhibition of the cholesterol transporter activity of NPC1 in cells that express both ACE2 and TMPRSS2, considerably reduces SARS-CoV-2 infectivity, evaluated as early as 4 h post-infection." (PMID 39707537, 2024). "Antiviral capacity of certain Phe(3-Am)-based matriptase/TMPRSS2 inhibitors against IAV subtypes H1N1 and H9N2 was also determined using an in vitro post-infection antiviral plaque assay." (PMID 39025978, 2024). "During infection, SARS-CoV-2 uses transmembrane serine protease 2 (TMPRSS2) and the ACE2 receptor to infect the host cell and the RNA polymerase to synthesize viral proteins." (PMID 38390960, 2024). "Subsequently, the transmembrane protease serine 2 (TMPRSS2) cleaves ACE2 and activates the S protein, facilitating viral entry and the infection of host cells." (PMID 39519859, 2024). "Furin enzymes or the host cell proteases, such as TMPRSS2, which cleave the S protein into S1 and S2, can also modify SARS-CoV-1 and SARS-CoV-2 and facilitate the infection." (PMID 39126095, 2024). "Significant changes were only found for TMPRSS2 at later time points in SARS‐CoV (48 hpi) and MERS‐CoV (72 hpi) infection compared to mock‐infected controls." (PMID 38623540, 2024). "At a multiplicity of infection (MOI) of 0.01, the multistep growth of Delta in Vero cells and VeroE6/TMPRSS2 cells was greater than that of XBB.1 and XBB1.5, while the growth curves of XBB.1 and XBB.1.5 were almost comparable." (PMID 38332154, 2024). "R203M and S202R substitutions in the WA1 background increased viral titers 72 hours after infection in A549-ACE2, Vero-TMPRSS2, and Huh7.5-ACE2/TMPRSS2 cell lines suggesting this enhancement is not restricted to our model cell lines." (PMID 39571001, 2024). "First, if ACE2 and TMPRSS2 are present at the luminal surface of the BBB, it can result in a direct infection of the endothelium." (PMID 38793666, 2024). "In comparison to DPP4 alone, the infection levels in cells co-transfected with DPP4 and TMPRSS2 are significantly higher, underscoring the critical role of TMPRSS2 in facilitating viral entry." (PMID 40295839, 2024). "During the infection of SARS-CoV-2, the spike proteins are cleaved and activated by transmembrane serine protease 2 (TMPRSS2) and furin, which interact with its cellular receptor, angiotensin-converting enzyme 2 (ACE2), to enter and infect host cells." (PMID 38686388, 2024). "Basal cells seem to be more or less spared from infection by SARS-CoV-2, although the cells carry ACE2 and TMPRSS2 on their surface." (PMID 39337465, 2024). "To enhance the infection readout of SARS-CoV-2, we used three transgenic cell lines expressing the angiotensin-converting enzyme 2 (ACE2) or the transmembrane protease (TMPRSS2), namely A549-ACE227, Huh7-ACE227, and VeroE6-TMPRSS228." (PMID 38879641, 2024). "Expression of specific protein markers such as TMPRSS2, ACE2, Alix, TSG101, CDs, TLRs, TNF-α, and others were altered in infection-derived EVs when compared to control-derived EVs after FCoV infection." (PMID 39091390, 2024). "TMPRSS2, known for activating influenza and SARS-CoV, also contributes to the infection process of SARS-CoV-2 in addition to the ACE2 receptor." (PMID 37809955, 2023).
infection (continued). "In the case of the transmembrane protease TMPRSS2, effective infection with SARS-CoV-2 requires angiotensin-converting enzyme 2 (ACE2) and TMPRSS2 to be co-expressed on the same cell membrane." (PMID 36674896, 2023). "However, that is controversial since ACE2 and TMPRSS2 are not co-expressed on a cellular level in testicular tissue, a fact that suggest the testis would not be susceptible to infection." (PMID 37497433, 2023). "In this review, an overview of two proteases that play an important role in the infection by SARS-CoV-2 that is responsible for COVID-19 pandemic, the viral protease MPro and the host protease TMPRSS2, has been presented." (PMID 37375781, 2023). "In the present study, SARS-CoV-2pp infection was increased by overexpression of ACE and significantly increased by coexpression of ACE2 and TMPRSS2." (PMID 36995225, 2023). "Multiple cell assay systems expressing infection-aiding proteins, including ACE2 and TMPRSS2 in the cell lines Vero E6, NCI-H460, and 293T, were employed in this report, coupled with the Vpps derived from the wild-type or the other variants." (PMID 37642993, 2023). "We used the rescued strain rSczy3 to infect CEKs and performed qRT-PCR to evaluate the relative expression levels of CTSL, CTSB, Abl1, Abl2, IFITM3, ADAM17, TMPRSS2, NRP1, and CD74 at 12 and 24 h post-infection." (PMID 37376546, 2023). "The nasal epithelium seems to be the first site of the respiratory system in the process of SARS-CoV-2 infection, and key permissive factors of infection, including ACE2, TMPRSS2, and furin, were shown to be highly expressed in the whole respiratory tract." (PMID 37196111, 2023). "Loci exhibiting the strongest stimulation by infection and repression by remdesivir included several proteases (TMPRSS4, TMPRSS6, TMPRSS11D, TMPRSS11E) closely related to TMPRSS2, a host factor during SARS-CoV-2 receptor-mediated endocytosis." (PMID 37205380, 2023). "The increased infection of brains by BA.5 and XBB over BA.1 in K18-hACE2 mice may be associated with the enhanced fusion activity of the later omicron variants, which is usually associated with an enhanced ability to utilize TMPRSS2 and/or increased binding affinity for ACE2." (PMID 38075874, 2023). "MS-275, a pharmacological HDAC1-3 inhibitor, was found to markedly increase SARS-CoV-2 replication and productive infection through the induction of ACE2 and TMPRSS2 expression." (PMID 38162580, 2023). "In contrast, infection of nasal ALI by BA.1 was completely insensitive to blockade by camostat, suggesting the use of a divergent entry pathway that is TMPRSS2-independent." (PMID 37425811, 2023). "Previous studies have suggested that TMPRSS2 and CTSL/CTSB inhibitors effectively prevent the infection of other coronaviruses, including SARS-CoV, MERS-CoV, and human coronavirus (HCoV)-229E58–60." (PMID 37990007, 2023). "Both teams also showed that NRP1 potentiates and enhances SARS-CoV-2 entry and infection, in the presence of ACE2 and TMPRSS2, consistent with the role of NRP1 as co-receptor." (PMID 37047226, 2023). "It has been reported that efficient infection of SARS-CoV and SARS-CoV-2 requires sequential cleavage of S by furin at the S1/S2 site and then by TMPRSS2 at the S2’ site or by CTSL at two specific sites in endosome when TMPRSS2 expression is repressed." (PMID 37196033, 2023). "Prior to infection we confirmed the expression of ACE2 and Transmembrane Serine Protease 2 (TMPRSS2) in our in vitro airway epithelium models." (PMID 37006263, 2023). "Our in vitro models support the conclusion that cells are more responsive to nicotine at the ALI than when submerged and that nicotine alone increased ACE2 levels (except in the cloud chamber), TMPRSS2 activity, and SARS-CoV-2 pseudoparticle infection." (PMID 37037851, 2023).
infection (continued). "This study highlights a previously unrecognized effect of HDAC1-3 inhibition in increasing SARS-CoV-2 cell entry, replication and productive infection correlating with increased expression of ACE2 and TMPRSS2." (PMID 38162580, 2023). "Transmembrane protease serine 2 (TMPRSS2) and the paired basic amino acid cleaving enzyme (FURIN) also play an important role in the infection process since they facilitate the priming of the spike protein." (PMID 36674607, 2023). "Alveolar cells also express the transmembrane serine protease 2 (TMPRSS2) enzyme, which is important in priming the S (spike) protein of SARS-CoV-2, which in turn facilitates infection of alveolar cells." (PMID 36849892, 2023). "In line with previous studies, the infection of atto647N-SARS-CoV-2 VLPs is in an ACE-2-dependent and TMPRSS2-dependent manner." (PMID 36560829, 2022). "A low expression of host factors involved in the first steps of infection such as the entry receptor ACE-2 and the transmembrane serine protease 2 have been suggested." (PMID 35663467, 2022). "Conversely, infection completely overlaps where ACE2 and TMPRSS2 co-localize in the tertiary bronchi, bronchioles, and alveoli." (PMID 35255100, 2022). "In fact, SARS-CoV-2 uses ACE2, combined with the transmembrane protease serine 2 (TMPRSS2), as the main molecular complex for the host cell infection." (PMID 35455008, 2022). "SARS-CoV-2 primarily targets the respiratory tract and infection is mediated by Spike protein binding to human angiotensin-converting enzyme (ACE2), where the transmembrane protease serine 2 (TMPRSS2) triggers fusion of the viral and cell membranes." (PMID 35049501, 2022). "The successful infection of Rhileki cells with multiple SARS-CoV-2 clinical isolates suggests the presence of functional bat ACE2 and TMPRSS2 in these cells, which is necessary for virus attachment and fusion." (PMID 35638834, 2022). "The infection and viral entry of SARS-CoV-2 into the cell is mediated by angiotensin ACE-2, transmembrane serine protease 2 (TMPRSS2) and cathepsin L, which cleaves the spike protein on the viral particle to allow engagement with ACE-2." (PMID 35719336, 2022). "Here, we connect the ability of SERPINE1 to inhibit TMPRSS2 with a reduction in SARS-CoV-2 entry and infection." (PMID 35532162, 2022). "Since the spike protein binds ACE2 to gain cell entry where transmembrane serine protease 2 (TMPRSS2) and paired basic amino acid cleaving enzyme (FURIN) are important for infection, expression levels of the latter two were studied." (PMID 35631029, 2022). "The cells used in this study were Huh7.5.1 for OC43 and 229E infections and Huh7.5.1 cells overexpressing ACE2 and TMPRSS2 to optimize SARS-CoV-2 infection." (PMID 35562967, 2022). "Next, the sensitivity of spike protein-induced cell–cell fusion to metalloprotease inhibition was examined in infection-competent Huh-7 cells, which endogenously express the ACE2 receptor but employ a TMPRSS2-independent mechanism of SARS-CoV-2 entry." (PMID 36298651, 2022). "Fusion luciferase activity was similar in TMPRSS2(-) 293T-ACE2 cells under all four conditions and was equally less efficient than that in TMPRSS2(+) cells, suggesting that TMPRSS2 confers an advantage to the SARS-CoV-2 in fusion (and hence infection)." (PMID 36438831, 2022). "In order to further explore our PV entry and infection findings, we studied the expression of ACE2 and TMPRSS2 across our target cells by qPCR on RNA extracts from cell lysates." (PMID 35075452, 2022). "When SARS-CoV-2 first enters the host respiratory tract, it initiates infection through the binding of the spike protein with Angiotensin-converting enzyme II (ACE2) receptor, and then utilizes transmembrane protease serine 2 (TMPRSS2) to enter host cells." (PMID 35874958, 2022).